TLR2 (toll like receptor 2)
Diseases named in the same sentence as TLR2 in open-access papers (continued):
Sharing a sentence is not in itself a finding about the gene and the disease.
endometritis (18 papers, 2014 to 2025). An acute or chronic, usually bacterial infectious process affecting the endometrium. "Gene expression levels were considerably higher in endometritis-affected buffaloes than in resistant ones for the genes A2M, TLR2, IRAK3, CCl2, FCAMR, iNOS, ADAMTS20, KCNT2, MAP3K4, MAPK14, FKBP5, and EPHA4." (PMID 38459095, 2024). "SNPs in the TLR4 and TLR2 genes and endometritis tolerance in buffalo have been elaborated." (PMID 37368756, 2023). "The suppression of TLR2/4-mediated NF-κB activation can relieve endometritis." (PMID 35100093, 2022). "We found CT135 activates the NLRP3 inflammasome through TLR2/MyD88 signaling pathway as a pathogenic strategy to evade neutrophil host defense, however, this strategy conjointly caused NLRP3 dependent macrophage-associated endometritis." (PMID 34526512, 2021). "In the present study, an in vitro model of LPS-induced human endometrial epithelial cells (HEnEpCs) was established to investigate whether USF2 can induce transcriptional activation of TREM1 and promote endometritis by regulating TLR2/4-NF-κB signaling pathway." (PMID 35100093, 2022). "The test showed that berberine and carvacrol downregulated the mRNA expression of TLR2 and TLR4 in the uterine tissues of endometritis mice." (PMID 40431224, 2025). "Collectively, USF2 promotes endometritis by upregulating TREM1, thereby activating TLR2/4-NF-κB pathway." (PMID 35100093, 2022). "During endometritis, TLR6 transcripts increased dramatically and TLR2 constitutes a heterodimer, a link to the ligands to stimulate an inflammatory reaction." (PMID 33426032, 2020). "The ability of endometrial cells to detect and respond to bacterial lipopeptides via TLR2/TLR1 and TLR2/TLR6 is probably important for the onset and persistence of endometritis in cattle." (PMID 24437488, 2014). "However, the knockdown of TLR2/TLR4 significantly reduced inflammatory responses, downregulated NF-κB/p65, and elevated Nrf2 levels, thereby ameliorating endometritis." (PMID 39408650, 2024). "The levels of the PRLR, LTF, CLA-DRB3.2, beta defensin, TLR2, TLR4, and CCL5 genes were significantly up-regulated in postparturient goats with endometritis compared to tolerant ones, while the GPX4, GST, SOD3, CAT, and ATOX1 gene patterns demonstrated the opposite tendency." (PMID 39195794, 2024). "Moreover, a study revealed that interferon-tau (IFN-τ) prevents S. aureus-induced endometritis by downregulating the expressions of NF-κB, matrix metalloproteinase 9 (MMP 9), TLR2, TNF-α, IL-1β, and IL-6 levels." (PMID 39408650, 2024). "Additionally, in contrast to cows with sub-clinical endometritis, the gene expression profiles of C3, CXCL8, LTF, TLR2, and TRAPPC13 were temporally changed in healthy cows’ circulating WBC during the postpartum period." (PMID 37756095, 2023). "In addition, IFN-τ inhibited the expression of TLR2, thereby blocking the activation of the NF-κB and MAPK signaling pathways and abating endometritis." (PMID 28331850, 2017).
staphylococcus aureus infection (18 papers, 2013 to 2024). An infectious process in which the bacteria Staphylococcus aureus is present. "Genetic diversity in the TLR2 gene is a risk factor for staphylococcus infection, and TLR2−/− mice are susceptible to S. aureus." (PMID 28078083, 2017). "In addition, Se deficiency facilitates inflammation following Staphylococcus aureus infection by regulating TLR2/NF-κB pathway in the murine mammary gland and macrophages." (PMID 32733409, 2020). "TLR2 recognizes Gram-positive PAMPs such as lipoprotein and peptidoglycan, and several studies have shown the importance of TLR2 in Staphylococcus aureus infection." (PMID 37237940, 2023). "For instance, Staphylococcus aureus infection augments TLR2 mRNA expression in astrocytes, and TLR2 knock out mice exhibit attenuated release of TNF and IL-1β." (PMID 35250814, 2022). "In the Staphylococcus aureus infection rat model, RP105 activation in macrophages induces the accumulation of TLR2 and increased TLR2-associated inflammatory cytokines production via a MyD88 axis." (PMID 34414191, 2021). "Human corneal epithelial cells (HCECs) express TLR2, which responds to Staphylococcus aureus infection through the expression and secretion of pro-inflammatory cytokines and β-defensin-2 (hBD2)." (PMID 30574051, 2018). "TLR2 is known to participate in autophagy activation upon Listeria monocytogenes and Staphylococcus aureus infections in murine macrophages." (PMID 27242971, 2016). "Expression of TLR2 in the host is important for clearance of Staphylococcus aureus infection and host survival." (PMID 24810614, 2014). "TLR2/4 was found to modify NET formation in response to Staphylococcus infection but not to PMA stimulation." (PMID 30936875, 2019). "There is a negative correlation between PPP1R11 and TLR2 levels in white blood cell samples isolated from patients with Staphylococcus aureus infections." (PMID 27805901, 2016). "In contrast to our in vitro data, in the rodent models of Staphylococcus aureus infection used, we could not demonstrate a significant induction the TLR2 gene expression." (PMID 28428684, 2017).
ulcerative colitis (18 papers, 2010 to 2025). An inflammatory bowel disease involving the mucosal surface of the large intestine and rectum. "Frequencies of carriers of at least one short (S-allele) for the intron 2 microsatellite repeat polymorphism or at least one Arg753Gln allele in the TLR2 gene in the specific phenotypic subgroups for ulcerative colitis." (PMID 28388655, 2017). "In ulcerative colitis (UC) patients, KLF4, CFTR, BMP2, TLR2 showed significantly lower expression in UC-associated cancer." (PMID 35733095, 2022). "Similarly, Clostridium butyricum has been found to regulate TLR2 expression in Interstitial cells of Cajal in ulcerative colitis." (PMID 33596997, 2021). "The TLR2/NF-κB signaling pathway plays an important role in the pathomechanism of ulcerative colitis (UC); acupuncture and moxibustion can improve the damage in colonic tissues of UC, but the regulatory mechanism remains unknown." (PMID 26339273, 2015). "The identification of TLR2, IFNG, and CD163 as hub genes suggests their potential utility as predictive biomarkers for ulcerative colitis diagnosis and disease monitoring." (PMID 41300749, 2025). "The wild-type (WT), TLR4, TLR2, and IL-10 knockout (-/-) germ-free mice grown were with or without BF colonization for 28 days, and then administered 1% DSS in drinking water for 7 day to induce acute ulcerative colitis." (PMID 28683149, 2017). "However, we report for the first time that expression of transcripts for both TLR-2 and TLR-4 was similar in crypt epithelial cells isolated from histologically normal and inflamed parts of colectomy specimens with left-sided ulcerative colitis." (PMID 24828022, 2014).
acute myeloid leukemia (17 papers, 2016 to 2025). Acute myeloid leukemia (AML) is a group of neoplasms arising from precursor cells committed to the myeloid cell-line differentiation. "The GSEA results showed that TLR2 was associated with acute myeloid leukemia (AML), and the study demonstrated a significant association between TLR2 polymorphisms and the risk of serious infections in AML patients." (PMID 39713769, 2024). "For example, by secreting palmitoylated proteins through EV, acute myeloid leukemia (AML) cells activate toll-like receptor 2 (TLR2), a receptor that mediates activation of the immune system." (PMID 37759431, 2023). "Similarly, palmitoylated proteins on acute myeloid leukemia (AML)-derived extracellular vesicles contribute to TLR2 activation to promote myeloid-derived suppressor cell (MDSC) reprogramming." (PMID 39877903, 2025). "In acute myeloid leukemia (AML), tumor-derived extracellular vesicles (EVs) activate TLR2 signaling on monocytes via their surface palmitoylated proteins, inducing their differentiation into immunosuppressive CD14+HLA-DRlow MDSCs." (PMID 40977744, 2025). "In a pursuit to further refine the targeting for acute myeloid leukemia (AML), we harnessed the maleic imide and thiol reaction mechanism, facilitating the coupling of Toll-like receptor 2 (TLR2) peptides to the liposomes’ surface via maleic imide." (PMID 38812031, 2024). "In other hematological cancers, such as acute myeloid leukemia (AML), the mRNA expression levels of TLR2 and TLR4, but not of TLR9, were increased, contrary to what was observed in ALL, and expression of TLR7 and 9 was decreased in chronic myeloid leukemia (CML)." (PMID 34567117, 2021).
chronic obstructive pulmonary disease (17 papers, 2006 to 2025). A chronic and progressive lung disorder characterized by the loss of elasticity of the bronchial tree and the air sacs, destruction of the air sacs wall, thickening of the bronchial wall, and mucous accumulation in the bronchial tree. "TLR2 is regulated in chronic obstructive pulmonary disease (COPD) and predominantly detects invasive Gram-positive bacteria, mycobacteria, and fungi." (PMID 34770863, 2021). "Importantly, SAA has been described as an innate regulator of granulomatous lung inflammation in sarcoidosis acting through Toll-like receptor-2, as well as mediator of glucocorticoid refractory lung inflammation in chronic obstructive pulmonary disease (COPD)." (PMID 29617422, 2018). "For instance, in diabetic mice macrophage-dependent, IL-1β production induced by toll-like receptor 2 (TLR2) and NLRP3 inflammasome activation may lead to cardiac arrhythmias." (PMID 34387811, 2022).
injury (17 papers, 2008 to 2023). Damage inflicted on the body as the direct or indirect result of an external force, with or without disruption of structural continuity. "A recent study by Hauk and colleagues showed that intravitreal injection of toll-like receptor 2 agonist Pam3Cys (caused lens injury) can induce glial activation and upregulations of GFAP and CNTF, which significantly stimulated retinal ganglion cell axon regeneration into the injured optic nerve." (PMID 20169166, 2010). "In summary, this work demonstrates that the SAA1/TLR2 axis is a critical mediator for migration of HSCs during acute liver injury." (PMID 34113824, 2021). "A previous study found that peripheral blood leukocytes from trauma patients with the TLR2 rs3804099 CC genotype produce greater amounts of IL-10, IL-8, and TNF-α than those having the TT genotype, after bacterial lipoprotein stimulation." (PMID 32576967, 2020). "We have demonstrated that systemic activation of toll-like receptor 2 induces infiltration of leukocytes, mainly neutrophils and inflammatory monocytes, to the developing brain of mice and exacerbates HI brain injury." (PMID 30376851, 2018). "Based on these data, we reasoned that TLR2-expressing satellite glial cells or macrophages in the DRG might respond to nerve injury and indirectly induce CCL2/MCP-1 expression in DRG neurons after peripheral nerve injury, thus enhancing macrophage infiltration." (PMID 21951975, 2011). "rhPRG4 reduced neuroinflammation and influx of monocytes in a rat model of traumatic brain injury, mediated by its regulation of the ERK1/2 pathway, downstream of CD44 and TLR2/4 engagements." (PMID 34992596, 2021). "In this context, signaling of HA fragments via TLR2 and TLR4 was shown to regulate the inflammatory response to BLM-induced lung injury and promote recovery and repair, at least in the acute BLM model." (PMID 28836991, 2017). "Moreover, it can inhibit C. albicans-induced macrophage stimulation (reduced activity of TLR-2, and TNF-α expression), and exhibits antifungal and anti-inflammatory action in a lung injury mouse model." (PMID 36551434, 2022). "PMN from trauma patients show reduced expression of CD16, TLR2, and TLR4." (PMID 34520397, 2021). "Finally, day 1 trauma patients (n = 9) showed similar elevations in free heme compared with that seen after murine liver injury, and circulating PMN showed similar TLR2 reduction compared with volunteers (n = 6)." (PMID 34520397, 2021).
liver disease (17 papers, 2012 to 2024). "Meanwhile, viral load, IL-6 and TLR2 genotypes were independent risk factors for progression of liver disease from active hepatitis state to cirrhotic liver disease." (PMID 35119591, 2023). "Evermore, multivariate regression analysis of the current findings revealed that IL-6 and TLR2 genotypes (SNP; rs3804099) were independent risk factors for progression of liver disease from inactive carrier state to active hepatitis state." (PMID 35119591, 2023). "Wild type haplotype (TLR2 ins/ins- IL28B C/C) was also found associated with older age in patients with an hepatic diseases (in CIR and in HCC p = 0.038 and p = 0.020, respectively) supporting an effect of innate immunity in the liver disease progression." (PMID 27183918, 2016). "Intriguingly, specific TLR polymorphisms, mainly the TLR2 −196 to −174 ins/del, influence the extent of TLR2 expression and have been associated with more advanced liver diseases." (PMID 27183918, 2016). "Recently, it has been shown that different combinations of IL28B genotype and toll-like receptor-2 (TLR-2) variants are associated with different manifestations of HCV-related liver disease and lymphoproliferative diseases." (PMID 27917361, 2016). "In the present study we demonstrated that the multilocus TLR2-ins/ IFNL3 T genotype was a significant factor for development of HCV-related liver diseases, and that the impact of rare PD-1.6 variant in Italian population is responsible for the discrepancy between Asian and European results." (PMID 30930876, 2019). "In addition, the TLR2 ins/ins-IL28B-C/C haplotype not only showed a potential protective effect against HCV infection but also an association with older patients having a liver diseases (CIR and HCC), thus, suggesting that the protective effect associated with this haplotype decreased with age." (PMID 27183918, 2016). "Studies have shown that Escherichia coli strains isolated from the intestinal tract of steatotic liver disease patients can translocate to the liver via the TLR2/NLRP3 pathway." (PMID 39796579, 2024). "Overactivation of TLR2 stimulates Kupffer cells (liver macrophages) and HSCs, promoting the progression of steatotic liver disease." (PMID 39796579, 2024). "Our findings link an increase in Enterococcus with induction of hepatic inflammation, via the pathogen-recognition receptor TLR2, and progression of liver disease." (PMID 29038503, 2017). "This indicates that viable Enterococcus reaches the liver and mediates ethanol-induced liver disease via binding to TLR2 on Kupffer cells and induction of hepatic inflammation." (PMID 29038503, 2017). "From these studies, we know that TLR2, TLR7 and TLR9 play key roles in liver diseases and TLR2 has an potential function in the regulation of tumor tolerance, cancer progression and metastasis." (PMID 22815694, 2012). "Therefore, the purpose of the current research is to investigate the role of IL-6 and TLR2 gene polymorphism in chronic active hepatitis B and how they affect the progression of HBV-associated liver disease (liver cirrhosis and HCC)." (PMID 39071840, 2024). "In addition to the involvement of TLR4 in liver disease, TLR2 signaling contributes to the pathogenesis of liver injury." (PMID 35231062, 2022). "Therefore, a longitudinal study could aid in more precise detection of the actual impact of IL-6 levels and TLR2 rs3804099 SNP variation on liver disease progression and outcome in HBV patients." (PMID 39071840, 2024). "TLR2, TLR3, TLR7 and TLR9 have a crucial role in host defense against HCV infection and HCV liver diseases." (PMID 27183918, 2016). "TLR2 is one of the most common TLRs and is widely expressed on parenchymal and nonparenchymal liver cells mediating liver disease pathogenesis, including alcoholic liver disease and the nonalcoholic steatohepatitis." (PMID 36313326, 2022).
liver disease (continued). "Notably, the in vivo depletion of SAA1 in C57/BL6 mice significantly reduced the recruitment of HSCs and altered the expression of TLR2 at the site of injury, indicating that SAA1/TLR2 axis plays a critical role for inducing the recruitment of HSCs during hepatic disease response." (PMID 34113824, 2021). "The increased TLR1/2, TLR2/6, and TLR4 expression may lead to exaggerated immune responses triggered by bacterial infection in HBV-related ACLF patients, and thus promotes the deterioration of liver disease." (PMID 29218046, 2017).
multiple sclerosis (17 papers, 2011 to 2026). A progressive autoimmune disorder affecting the central nervous system resulting in demyelination. "TLR2 upregulation has been reported in multiple sclerosis patients and in experimental autoimmune encephalomyelitis (EAE), a mouse model for multiple sclerosis." (PMID 33013394, 2020). "Within the CNS, HMW HA was reported to downregulate the proliferation of astrocytes, while the HA-dependent activation of TLR2 on immature oligodendrocytes has implications for remyelination in the case of multiple sclerosis." (PMID 31405034, 2019). "In multiple sclerosis, heightened TLR2/4/9 signaling agents that inhibit pyrimidine synthesis may increase IL-10 and reduce antimycobacterial immunity." (PMID 41892000, 2026). "Although celatrol has a powerful anti-inflammatory effect, few studies have examined whether such effects are brought out by inhibiting innate immunity, especially TLR2, which has only been reported in multiple sclerosis and RA." (PMID 36034791, 2022). "The PE DHC lipids also enhance (TLR2)-dependent murine experimental autoimmune encephalomyelitis (EAE), a model for multiple sclerosis." (PMID 21347306, 2011).